TNF (tumor necrosis factor)
Diseases named in the same sentence as TNF in open-access papers (continued):
Sharing a sentence is not in itself a finding about the gene and the disease.
rheumatoid arthritis (continued). "TNFα inhibitor therapy has greatly improved the treatment of patients with rheumatoid arthritis, however at least 30% do not respond." (PMID 22685579, 2012). "Continuous TNF stimulation promotes proliferation and new blood vessel formation by HUVEC - the process of TNF-induced angiogenesis, which plays a role in the pathogenesis of solid tumours, multiple myeloma and rheumatoid arthritis." (PMID 23281897, 2012). "Baseline serum N-glycan hypogalactosylation, an index previously correlated with hypogalactosylation of IgG N-glycans, did not distinguish patients with rheumatoid arthritis who were likely to experience a favorable clinical response to MTX or TNF blockade." (PMID 22390545, 2012). "This study identifies IL-33 as a critical regulator/enhancer of TNF-α-induced functions in RA-SFs, pointing to a central role of this cytokine in the perpetuation of pro-inflammatory and pro-destructive processes in rheumatoid arthritis (RA) and other inflammatory and degenerative diseases." (PMID 22246057, 2012). "In recent years, anti–tumor necrosis factor (anti-TNF) therapies have been routinely used for the management of rheumatoid arthritis (RA) patients who have failed traditional nonbiologic disease-modifying antirheumatic drugs (DMARDs)." (PMID 22422731, 2012). "Interestingly, IL-17 was shown to have additive effects with TNF-α and IL-1 on the up-regulation of TSG-6 expression in the synovium of patients with rheumatoid arthritis." (PMID 22452753, 2012). "VEGF is upregulated by inflammatory cytokines such as IL-6, tumor necrosis factor-α (TNF-α), and IL-8, and may play a major role in inflammatory diseases such as rheumatoid arthritis, asthma, Churg-Strauss syndrome and Behcet's disease." (PMID 22162767, 2011). "Tumor necrosis factor α (TNF-α) is a key regulator of inflammation and rheumatoid arthritis (RA)." (PMID 21423713, 2011). "Histoplasmosis occurs in patients with rheumatoid arthritis (RA) who receive corticosteroid therapy, disease modifying antirheumatic therapies such as methotrexate, and has been reported in post-marketing surveillance of patients receiving anti-tumor necrosis factor (TNF) therapy." (PMID 21605439, 2011). "Similarly, TNFα-induced expression of matrix metalloproteinases (MMP1 and MMP3) in synovial fibroblasts from a rheumatoid arthritis patient was suppressed by P-Dex." (PMID 20836843, 2010). "We present a case report of a man on anti-TNF therapy for rheumatoid arthritis presenting with an acutely red, swollen, non-tender penis and scrotum presumed to be infective." (PMID 20062693, 2009). "Most therapies for rheumatoid arthritis, specifically biologics, are targeted towards TNFα protein and not towards its activated signalling pathways." (PMID 19144181, 2009). "Third, the age and sex distribution of patients in this report mirrors that for patients with pulmonary NTM disease and rheumatoid arthritis independent of anti–TNF-α therapy." (PMID 19861045, 2009). "Thus, our data seem to be more in line with data from mice suggesting that the interaction of TNF-α with TNFR2 on Tregs promotes their expansion and upregulation of FOXP3 than with the data from studies of human rheumatoid arthritis." (PMID 19343213, 2009). "Different types of anti-TNF drugs were developed for patients with non-TB related inflammatory diseases such as rheumatoid arthritis and Crohn's disease." (PMID 17953477, 2007). "Another interesting observation was that in these osteoarthritis cultures of synovial cells, IL-1β production was independent of TNF-α, in contrast to the situation in rheumatoid arthritis." (PMID 17177994, 2006). "Although anti-TNF treatment is unlikely to cure the disease (as in the case of rheumatoid arthritis and Crohn's disease), it would still offer symptomatic relief and quality of life improvement." (PMID 17205112, 2006).
rheumatoid arthritis (continued). "As indicators of responsiveness to a tumour necrosis factor (TNF)α blocking agent (infliximab) are lacking in rheumatoid arthritis, we have used gene profiling in peripheral blood mononuclear cells to predict a good versus poor response to infliximab." (PMID 16817978, 2006). "In any case, it is worth mentioning that our group and others have previously found that other biological agents (anti-TNF-α) are also able to enhance the number and function of TREG cells in patients with an autoimmune/inflammatory disease (rheumatoid arthritis)." (PMID 16677395, 2006). "Recently, we reported that tumour necrosis factor (TNF)-α, IL-1α, IL-1β and IL-17 enhance Cyp7b mRNA expression and induce a concomitant increase in the formation of 7α-OH-DHEA by fibroblast-like synoviocytes (FLS) from rheumatoid arthritis patients." (PMID 16277680, 2005). "The production of tumor necrosis factor α (TNF-α) and interleukin-1β (IL-1β) by monocytes is strongly induced by direct contact with stimulated T lymphocytes, and this mechanism may be critical in the pathogenesis of rheumatoid arthritis (RA)." (PMID 15540281, 2004). "Notably real-world studies and meta-analyses in rheumatoid arthritis have not shown significant increase in MACE compared with disease modifying antirheumatic drugs (DMARDs) or anti-TNF agents." (PMID 41301759, 2025). "Tumor necrosis factor (TNF) inhibitors (etanercept, adalimumab, infliximab, golimumab, certolizumab pegol), T cell costimulatory inhibitors (abatacept), IL-6 receptor inhibitors (tocilizumab, sarilumab), and anti-CD20 antibody (rituximab) are biological DMARDs used for rheumatoid arthritis." (PMID 39897312, 2025). "However, 20–40 % of patients with rheumatoid arthritis do not respond to TNFα inhibitors, necessitating more precise therapeutic strategies for TNF inhibition." (PMID 40688496, 2025). "However, the elevated levels of IL-6 are observed in some but not all patients with rheumatoid arthritis, and there was not always a direct correlation with the increased levels of TNF-α, IL-1, or other proinflammatory cytokines." (PMID 40332498, 2025). "Lastly, the potential effects of J1/J2 on TNF-alpha and MCP-1 inflammatory cytokines were investigated, because they are deeply involved in the pathogenesis of numerous disease conditions such as neuroinflammatory diseases, rheumatoid arthritis, cardiovascular diseases, even cancer." (PMID 41141269, 2025). "Similarly, anti‐TNF‐α treatment downregulates IL‐18 but not IL‐12 in patients with rheumatoid arthritis." (PMID 38481033, 2024). "ESR1, TNF, SRC, HSP90AA1, and CASP3 further contribute to immunoregulation via distinct mechanisms: ESR1 influences the activity of T and B cells and plays a role in the treatment of sex-related autoimmune diseases, such as rheumatoid arthritis and systemic lupus erythematosus." (PMID 39717552, 2024). "In rheumatoid arthritis, the inhibitory effect of lipopolysaccharide (LPS) on IL-10 expression in fibroblast-like synoviocytes can be significantly reversed by shikonin due to the inactivation of the PKC-NF-κB pathway, thereby reducing the production of tumor necrosis factor-α (TNF-α)." (PMID 39444792, 2024). "S100A4 has also been shown to stimulate the production of the pro-inflammatory cytokines IL-1β, IL-6, and TNF-α from peripheral blood mononuclear cells (PBMC) isolated from patients with rheumatoid arthritis; however, these effects were not RAGE-dependent, but TLR-4-dependent." (PMID 39766257, 2024). "Additionally, a 17.6-year-old male with newly diagnosed rheumatoid factor (RF) positive rheumatoid arthritis did not respond to initial treatment with this drug before transitioning to anti-TNF medication." (PMID 39334678, 2024). "Among them, IMO-3100, a TLR7/9 dual antagonist of TLR7 and TLR9 can block the expression of IFN-β, TNF-α, and interleukin 17 (IL-17) and attenuate SLE, rheumatoid arthritis (RA) in a murine model." (PMID 36677692, 2023).
rheumatoid arthritis (continued). "The use of biological therapies, for example tumor necrosis factor (TNF)-α inhibitors and monoclonal anti-CD20 antibodies, is rapidly expanding as treatments of hematological and autoimmune diseases such as B-cell lymphomas, rheumatoid arthritis, inflammatory bowel diseases, and multiple sclerosis." (PMID 36941613, 2023). "In rheumatoid arthritis-FLS (RA-FLS), TNF-α induces several metabolic changes, including amino acid biosynthesis, purine metabolism, fatty acid metabolism and glycolysis." (PMID 36828912, 2023). "The TNF-alpha inhibitors markets do not represent a unified market which can function differently by indication, for example, rheumatoid arthritis where more treatments options are available and inflammatory bowel disease where severe consequences can occur with treatment failure." (PMID 37153785, 2023). "Increased TNF-α levels in patients with autoimmune disease led to the development of TNF-α inhibitors, such as infliximab and etanercept, which are very efficient in the management of rheumatoid arthritis, Crohn’s disease, ulcerative colitis, and other autoimmune disorders." (PMID 37570367, 2023). "Indeed, the application of over-sulfated 4S/6S CS showed a high inhibition of tumor necrosis factor-α (TNF-α), which is not only involved in inflammatory processes of bowel diseases, but also in other autoimmune diseases such as rheumatoid arthritis or psoriasis." (PMID 38068777, 2023). "Anti-tumor necrosis factor-alpha monoclonal antibody (anti-TNFα mAb) suppresses inflammation by inhibiting the activity of TNFα and is employed as a major therapeutic agent for immune-mediated inflammatory diseases such as inflammatory bowel disease (IBD) and rheumatoid arthritis (RA)." (PMID 36996146, 2023). "Tumor necrosis factor alpha (TNF-α), which enhances osteoclast activity and bone resorption, is one of the key inflammation mediators in rheumatoid arthritis (RA)." (PMID 36902687, 2023). "However, other authors reported lack of beneficial effect of ALA on serum TNF-α level in patients with rheumatoid arthritis." (PMID 35596774, 2022). "Pathogenesis mechanisms of SJIA were dysregulation of immune system, and overproduction of inflammatory cytokines [tumor necrosis factor-α (TNF-α), interleukin-1 (IL-1) and interleukin-6 (IL-6)] resembled those found in adult rheumatoid arthritis (RA)." (PMID 35906625, 2022). "In a previous study, we found that the inhibitory effect of ebosin on TNF-α secretion was stronger than other cytokines as IL-1β and IL-6 in the CIA rat model and FLS cells, implicating that ebosin may improve rheumatoid arthritis symptoms through the TNF-α signaling pathway." (PMID 35340587, 2022). "Prophylactic administration of a TNF-α inhibitor ameliorated glycocalyx degradation in response to low-dose endotoxin in healthy volunteers, and a combination therapy of methotrexate and/or a TNF-α inhibitor in rheumatoid arthritis patients decreased syndecan-1 for greater than 6 weeks." (PMID 35872762, 2022). "One of the modules (M7) identified in this analysis comprised a cluster of type I interferon-induced genes, which is consistent with earlier hypothesis-based findings in rheumatoid arthritis and IBD, where high type I IFN signatures correlated with poor response to TNF antagonists." (PMID 36153599, 2022). "Inflammatory cytokines such as interleukin 6 (IL-6), IL-1β, and tumor necrosis factor (TNF) have been shown to be biomarkers of both acute and chronic CHIKVD, with levels of these cytokines also commonly being elevated in autoimmune arthritides such as rheumatoid arthritis (RA)." (PMID 35254128, 2022).
rheumatoid arthritis (continued). "Anti-TNF-alpha therapy does not modulate leptin in patients with severe rheumatoid arthritis." (PMID 36291691, 2022). "RCT: randomized clinical trial; TNFi: tumor necrosis factor-alpha inhibitor; CVD: cardiovascular disease; CHF: congestive heart failure; RA: rheumatoid arthritis; DMARD: disease-modifying antirheumatic drug." (PMID 35915691, 2022). "According to what has been described in patients with postmenopausal osteoporosis or rheumatoid arthritis, the latter might be due to the capacity of CD8+ T lymphocytes to secrete pro-inflammatory mediators like TNF-α, finally facilitating the activity of osteoclasts." (PMID 36187089, 2022). "Although recent guidelines recommend that tapering of biologic disease-modifying anti-rheumatic drugs (bDMARDs) can be considered in patients with rheumatoid arthritis (RA), there has been little evidence supporting the strategy during the non-tumor necrosis factor inhibitor treatment." (PMID 35211491, 2022). "In vivo rat model of rheumatoid arthritis (RA), DEX suppresses NLRC5, therefore reducing cytokine levels of IL-1β, IL-6, IL-17A, and TNF-α." (PMID 35628263, 2022). "Thus, TNF-α and VEGF are important factors in the progression of rheumatoid arthritis." (PMID 35028065, 2022). "The unequal clinical efficacy of different anti-TNF agents between IBD and other chronic inflammatory diseases (e.g., rheumatoid arthritis) suggested that the effector mechanism of anti-TNF therapy in IBD may not be attributed to the TNF blockade alone." (PMID 35979230, 2022). "Moreover, the rates of NTM infection were significantly higher in rheumatoid arthritis patients receiving anti-TNF-α therapy than in those not receiving the therapy." (PMID 36505429, 2022). "According to the 2019 update of the EULAR recommendations for the management of rheumatoid arthritis, if a patient treated with TNF inhibitor is a primary non-responder or develops secondary non-responsiveness over time, the treatment with this drug should be discontinuated." (PMID 35216481, 2022). "IL-8 and tumor necrosis factor (TNF) α are involved in important pathophysiological processes in inflammatory bowel disease (IBD) and rheumatoid arthritis (RA)." (PMID 36505430, 2022). "It is observed in up to 2% of IBD patients treated with anti-TNF agents due to IBD, as well as other immune-mediated conditions, such as rheumatoid arthritis (RA) and ankylosing spondylitis." (PMID 33477990, 2021). "This protein inhibitor was verified to attenuate the disease models of sepsis, rheumatoid arthritis (RA) and inflammatory bowel disease (IBD) and reduce the secretion of TNFα." (PMID 34182543, 2021). "Indeed, exposure to IFN-α increased CD47 expression on monocytes, whereas TNF-α, a major cytokine produced during inflammatory responses to bacterial infections and rheumatoid arthritis, did not." (PMID 34068752, 2021). "This is because RTX has only approved for the treatment of non-Hodgkin’s B cell lymphoma, chronic lymphocytic leukemia, Wegener’s granulomatosis, and in patients with rheumatoid arthritis who are not responding to TNF-α blockers (U.S. Food and Drug Administration, 2012)." (PMID 34505112, 2021). "Rheumatoid arthritis (RA), inflammatory bowel disease (IBD), psoriatic arthritis (PsA), psoriasis (PS), and noninfectious uveitis (NIU) are induced by the abnormal secretion of TNF-α; thus, TNF-α can be classified as a key factor in the pathological development." (PMID 33800290, 2021). "Furthermore, the expression of membrane-bound PR3 is higher in patients with rheumatoid arthritis, whereas the cell surface expression of PR3 is further upregulated in the presence of pro-inflammatory cytokines, since PR3 proteolytically cleaves TNF-α to the active TNF-α form." (PMID 34869231, 2021). "Likewise, dysregulated TNF-α may contribute to the DOX-induced immunomodulation, since it participated in immune-inflammatory diseases such as rheumatoid arthritis and ulcerative colitis." (PMID 34943009, 2021).
rheumatoid arthritis (continued). "Proteins in the immune system, such as tumor necrosis factor-α (TNF-α), interleukins (ILs) 12 and 23, or interleukin (IL) 17 play a crucial role in the pathogenesis of many diseases such as psoriasis, psoriatic arthritis, rheumatoid arthritis, or ankylosing spondylitis." (PMID 34829797, 2021). "Biological therapies, such as TNF inhibitors (TNFi), are increasing remission (REM) rates in rheumatoid arthritis (RA) patients, although these are still limited." (PMID 34222289, 2021). "In rheumatoid arthritis, the effects of TNF-α and IL-6 are observed regardless of the length of the disease, but in SSc, IL-6 may have a minimal role in patients with a long disease course and IL-13 may have a limited role during the early disease stages." (PMID 34064515, 2021). "These reformulated drugs can also be tested for use in other diseases such as psoriasis, inflammatory bowel disease, rheumatoid arthritis, and ankylosing spondylitis, where non-selective TNF alpha-blockers have been approved but their use is limited due to demyelinating side effects." (PMID 34804701, 2021). "When compared to FLS from patients with early rheumatoid arthritis, FLS from patients with resolving synovitis have significantly elevated mitochondrial respiratory capacity in the resting state, and less fragmented mitochondrial morphology after TNFα treatment." (PMID 34512657, 2021). "Because etanercept is used to treat rheumatoid arthritis, rather than heart failure, it is possible that it has poor bio‐distribution into cardiac tissues and may not block locally produced TNF‐α." (PMID 34713972, 2021). "Anti-TNF therapies can manage inflammation in many human inflammatory diseases, e.g., chronic kidney disease (CKD), rheumatoid arthritis (RA), Crohn’s disease, psoriasis, psoriatic arthritis, and sepsis." (PMID 34975885, 2021). "Therefore, the SNPs in the TNF-α promoter may be related to HLA haplotypes and autoimmune diseases such as systemic lupus erythematosus (SLE) and rheumatoid arthritis (RA)." (PMID 30900134, 2020). "In contrast, stimulation of rheumatoid arthritis synovial tissue fibroblasts, bronchial epithelial cells, smooth mushle cells, umbilical vein endothelial cells and annulus fibrosus cells by TNF-α did not influence CXCL16 expression." (PMID 33552057, 2020). "In this study, tumor necrosis factor (TNF)-α was used to induce the proliferation and inflammatory process in RA-FLS, to explore the therapeutic potential of galuteolin in the treatment of rheumatoid arthritis." (PMID 33087158, 2020). "The primary objectives of this clinical trial is to study the clinical and pharmacoeconomic impact after 6 months of the use of the SinnoTest® predictive tool in patients with rheumatoid arthritis who have failed to a first anti-TNF biologic agent compared to usual care." (PMID 32867830, 2020). "In case of diseases, such as rheumatoid arthritis (RA), Crohn’s disease (CD), psoriasis, retinitis, multiple myeloma, diabetes, obesity, human immunodeficiency virus (HIV-AIDS)-mediated inflammations, and cognitive impairment, anti-TNF agents are the first drug of choice to lower the inflammation." (PMID 31991572, 2020). "IL-6, TNFα and B lymphocytes have been reported to play a crucial role in the inflammatory cascade taking place days before the manifestation of the most severe forms of SARS-CoV-2 infection, as well as in the physiopathological processes leading to rheumatoid arthritis." (PMID 33519443, 2020). "It is interesting to remark that exosomes produced by synovial fibroblasts from patients developing rheumatoid arthritis (but not from healthy controls) contain membrane-bound TNFα CD4+ T lymphocytes are a major cell population in the inflammatory infiltrate of rheumatoid arthritis patient joints." (PMID 32290050, 2020).